ATP2A2 (ATPase sarcoplasmic/endoplasmic reticulum Ca2+ transporting 2)
Description:
This magnesium-dependent enzyme catalyzes the hydrolysis of ATP coupled with the translocation of calcium from the cytosol to the sarcoplasmic reticulum lumen. Involved in autophagy in response to starvation. Upon interaction with VMP1 and activation, controls ER-isolation membrane contacts for autophagosome formation. Also modulates ER contacts with lipid droplets, mitochondria and endosomes. In coordination with FLVCR2 mediates heme-stimulated switching from mitochondrial ATP synthesis to thermogenesis (By similarity). [Isoform 2]: Involved in the regulation of the contraction/relaxation cycle. Acts as a regulator of TNFSF11-mediated Ca(2+) signaling pathways via its interaction with TMEM64 which is critical for the TNFSF11-induced CREB1 activation and mitochondrial ROS generation necessary for proper osteoclast generation. Association between TMEM64 and SERCA2 in the ER leads to cytosolic Ca(2+) spiking for activation of NFATC1 and production of mitochondrial ROS, thereby triggering Ca(2+) signaling cascades that promote osteoclast differentiation and activation.
Synonyms: SERCA2; ATP2B; DAR; DD; RHABDO2
Tractability: Small molecule: a drug acting on it is in phase 2 or 3 trials; a structure with a bound ligand is known; a high-quality ligand is known; it belongs to a druggable protein family. Antibody: its Gene Ontology location is reachable by antibodies, with high confidence; UniProt predicts a signal peptide or a membrane-spanning region. PROTAC: ubiquitination databases record sites on it; its protein half-life has been measured; a small molecule that binds it is known.
Target class: Enzyme; Hydrolase
Gene: Protein-coding gene on chromosome 12 (110,280,669 to 110,351,093, forward strand). Ensembl gene ENSG00000174437.
Subcellular location: Endoplasmic reticulum membrane; Sarcoplasmic reticulum membrane
Subcellular location (Human Protein Atlas): Nucleoplasm; Plasma membrane; End piece; Mid piece; Perinuclear theca; Primary cilium
Pathways (Reactome):
Hemostasis: Reduction of cytosolic Ca++ levels
Muscle contraction: Ion homeostasis
Signal Transduction: Pre-NOTCH Processing in Golgi
Transport of small molecules: Ion transport by P-type ATPases
Gene Ontology:
Molecular function: calcium channel regulator activity; calcium ion binding; enzyme binding; P-type calcium transporter activity; P-type calcium transporter activity involved in regulation of cardiac muscle cell membrane potential; protein binding; S100 protein binding; transmembrane transporter binding; ATP binding; ATP hydrolysis activity; lncRNA binding; nucleotide binding
Biological process: autophagosome assembly; autophagosome membrane docking; calcium ion import into sarcoplasmic reticulum; calcium ion transmembrane transport; calcium ion transport from cytosol to endoplasmic reticulum; endoplasmic reticulum calcium ion homeostasis; intracellular calcium ion homeostasis; positive regulation of endoplasmic reticulum calcium ion concentration; regulation of cardiac muscle cell membrane potential; cell adhesion; epidermis development; monoatomic ion transmembrane transport; positive regulation of heart rate; regulation of cardiac conduction; regulation of cardiac muscle cell action potential involved in regulation of contraction; regulation of cardiac muscle contraction by calcium ion signaling; response to endoplasmic reticulum stress; sarcoplasmic reticulum calcium ion transport; calcium ion transport; muscle system process; regulation of muscle contraction
Cellular component: endoplasmic reticulum; endoplasmic reticulum membrane; membrane; sarcoplasmic reticulum; sarcoplasmic reticulum membrane; plasma membrane; platelet dense tubular network membrane; ribbon synapse
Genetic constraint (gnomAD): Loss-of-function variants: 14 observed, 106.67 expected, observed/expected ratio (o/e) 0.13, 90% interval 0.086 to 0.2. The upper end of that interval is the gene's LOEUF score, 0.2, which puts it in group 1 of 6, group 1 being the genes least tolerant of losing a copy. Missense variants: 654 observed, 1,365.8 expected, observed/expected ratio (o/e) 0.48, 90% interval 0.45 to 0.51. Synonymous variants: 505 observed, 510.5 expected, observed/expected ratio (o/e) 0.99, 90% interval 0.92 to 1.07.
Homologues: Orthologues: chimpanzee ATP2A2 (99% identical), pig ATP2A2 (99% identical), rat Atp2a2 (99% identical), guinea pig ATP2A2 (98% identical), rabbit ATP2A2 (96% identical), macaque ATP2A2 (96% identical), mouse Atp2a2 (94% identical), tropical clawed frog atp2a2 (90% identical), zebrafish atp2a2b (87% identical), Drosophila melanogaster SPoCk (30% identical), Caenorhabditis elegans pmr-1 (29% identical), Caenorhabditis elegans catp-2 (22% identical), and 6 more. Paralogues in human: ATP2A1 (81% identical), ATP2A3 (74% identical), ATP2C1 (33% identical), ATP2C2 (31% identical), ATP2B1 (30% identical), ATP1A2 (29% identical), ATP2B3 (29% identical), ATP1A4 (29% identical), ATP1A1 (29% identical), ATP2B2 (29% identical), ATP2B4 (29% identical), ATP1A3 (29% identical), and 9 more.
Diseases named in the same sentence as ATP2A2 in open-access papers:
ATP2A2 is named in the same sentence as 144 diseases in open-access papers, as found by Europe PMC text mining. Sharing a sentence is not in itself a finding about the gene and the disease. The quoted sentences say what the papers report.
heart failure (69 papers, 2009 to 2026). Inability of the heart to pump blood at an adequate rate to meet tissue metabolic requirements. "mRNA levels for Atp2a2, which encodes sarco(endo)plasmic reticulum calcium-ATPase 2 pump (SERCA2) and is typically down-regulated in heart failure, were decreased in TM54 AAV9sc.GFP control mice, but restored in AAV9sc.PBD-treated mice." (PMID 38572067, 2024). "Reduced ATP2A2 expression is associated with cardiac failure, and normalizing ATP2A2 expression is being pursued as a therapeutic target in heart failure." (PMID 26001054, 2015). "This study investigates whether the BDNF Val66Met (rs6265) and ATP2A2 rs1860561 polymorphisms are associated with a differential therapeutic response to low-dose empagliflozin in patients with heart failure." (PMID 41007658, 2025). "Expression for proteins responsible for excitation–contraction coupling (Atp2a2/Serca2a, Cav1.2/Cacna1c, Ryr2) was dysregulated in MI animals, consistent with pathological remodeling associated with MI and progression to heart failure." (PMID 37801130, 2023). "ATP2A2 inhibition causes Ca2+ overload and cardiomyocyte dysfunction, and gene therapies enhancing ATP2A2 expression have been proposed for the treatment of heart failure." (PMID 35563680, 2022). "However, our studies with the mouse model of DD also reveal that loss of a single copy of Atp2a2 can lead to much more rapid decompensation, heart failure, and death in mice carrying an HCM mutation that increases myofibrillar Ca2+ sensitivity." (PMID 26064889, 2015). "Our selected candidates included many therapeutic targets for heart failure including Atp2a2, Bcl2, Sod2 and Sirt323,24,28,41." (PMID 31705051, 2019). "In the present study, our results showed that the binding of total AcH3, as well as the subtype AcH3K9, was reduced, and that the binding of active transcription factors GATA4 and Mef2c was decreased near the Atp2a2 promoter region after heart failure." (PMID 30286210, 2018). "This downregulation of ATP2A2 is typical of heart failure, and was also recently described in a rat model of right heart failure." (PMID 26252659, 2015). "Darier disease, which is pathophysiologically very similar to HHD as it is caused by mutations in ATP2A2 that encodes the SERCA2, thus upstream in the cells’ secretory pathway, is associated with heart failure as well as diabetes, cognitive impairment and several psychiatric disorders." (PMID 39241028, 2024). "Our results showed increased activity and binding of HDAC1 to the Atp2a2 promoter region, indicating that it might be a causal factor of SERCA2a downregulation mediated by hypoacetylation during TAC-induced heart failure in mice." (PMID 30286210, 2018). "NKX2-5, CAV1 and ATP2A2 in the integrin signaling and cardiac hypertrophy signaling (enhanced) pathways were also involved in the toxicity pathways such as failure of heart, congenital heart disease, congestive heart failure, dilation of heart chamber and dilation of left ventricle." (PMID 31948008, 2020). "In our study, inhibition of TBX5 was shown to dysregulate several genes such as DES, NKX2-5, ACTC1, MYH6, ATP2A2 and HSPB7, which further contributed to ICM-related diseases such as failure of heart and degeneration of heart." (PMID 32423033, 2020). "Integrating the results of the TBX5-targeted genes and the DEGs in toxicity pathways, we found that the dysregulation of TBX5-targeted genes, TNNT2, NPPA, TTN, ATP2A2, DES and SCN5A, contributed to the development of heart failure and arrhythmia." (PMID 32423033, 2020). "Moreover, this histological observation was supported by increased expression levels of heart failure markers, such as ANP and BNP, and physio-functional markers, such as Atp2a2, Myh6, and Myh7, which indicate contractility, cardiomyocyte size and LV wall thickness, respectively." (PMID 35008972, 2022).
heart failure (continued). "Interestingly, several genes including NKX2-5, ATP2A2 and CAV1 involved in these pathways were also found in toxicity pathways such as failure of heart, congenital heart disease, congestive heart failure, dilation of heart chamber and dilation of left ventricle." (PMID 31948008, 2020). "However, while these results provide compelling evidence that Atp2a2 heterozygosity does not impair cardiac function in middle-aged humans, they do not rule out the possibility that SERCA2 haploinsufficiency can increase susceptibility to disease progression and heart failure." (PMID 26064889, 2015).
Darier disease (59 papers, 2000 to 2026). Darier disease (DD) is a keratinization disorder characterized by the development of keratotic papules in seborrheic areas and specific nail anomalies. "Darier disease (DD) is a rare genetic disorder caused by mutations in the ATP2A2 gene, resulting in calcium dysregulation and impaired keratinocyte adhesion." (PMID 41466489, 2025). "In 1906, Kreibich first identified the localized pattern of Darier’s disease where only involved skin possessed ATP2A2 mutations." (PMID 40225094, 2025). "Darier disease is a rare autosomal dominant inherited skin disorder, caused by mutations in the ATP2A2 gene." (PMID 40443846, 2025). "Darier's disease (DD), also known as Darier‐White disease, is a rare autosomal dominant genodermatosis resulting from mutations in the ATP2A2 gene." (PMID 40051896, 2025). "While ATP2A2 is a monogenic cause of Darier disease (a skin disorder with neuropsychiatric abnormalities), the prevalence of epilepsy in this condition is higher than in the general population." (PMID 40699779, 2025). "Darier's disease and Acrokeratosis Verruciformis of Hopf can exhibit overlapping clinical features due to mutations in the same ATP2A2 gene." (PMID 40933297, 2025). "Darier′s disease (DD) is a rare, autosomal dominant genodermatosis caused by pathogenic variants in the ATP2A2 gene, which encodes the SERCA2 protein, an endoplasmic reticulum ATPase Ca2+ transporter." (PMID 40565511, 2025). "We identified a total of 189 patients with variants in the ATP2A2 gene and a diagnosis of Darier’s disease; of these, 92 were female, 64 were male, and for 33 the sex was not reported." (PMID 40565511, 2025). "The somatic mosaicism of ATP2A2 due to post-zygotic mutations is associated with acantholytic dyskeratotic nevi along the Blaschko lines, referred to as segmental Darier’s disease." (PMID 40565511, 2025). "Darier disease (DD) is a rare autosomal dominant genetic skin condition caused by mutations in the ATP2A2 gene, which encodes SERCA2, a calcium ion transporter within the endoplasmic reticulum." (PMID 38390850, 2024). "ATP2A2 gene mutation is specific for Darier disease, a genetic disease characterized by skin lesions associated with neuropsychiatric symptoms, mainly major depression (30%)." (PMID 39457478, 2024). "Defects in ATP2A2 associated with Darier disease result in both acantholysis and apoptosis, which are partly due to alteration in the synthesis, trafficking, and folding of desmosomal proteins, as well as abnormal cytokeratin expression." (PMID 39273660, 2024). "This is similar to Darier disease, which is caused by mutations in the ATP2A2 gene that encodes the sarcoendoplasmic reticulum Ca2+ pump (SERCA2)." (PMID 39241028, 2024). "ATP2A2 is associated with Darier's disease (OMIM #124200), whereas pathogenic variants of ATP2C1 cause Hailey–Hailey disease (OMIM #169600)." (PMID 38804677, 2024). "Darier disease (DD) is a rare, inherited multi-organ disorder associated with mutations in the ATP2A2 gene." (PMID 37978298, 2023). "Darier’s disease (DD) is a genodermatosis caused by mutations of the ATP2A2 gene leading to disrupted keratinocyte adhesion." (PMID 37496039, 2023). "Darier disease (DD) is an autosomal-dominant genodermatosis in which mutations in the ATP2A2 gene result in impaired intercellular adhesion and epidermal blistering." (PMID 36741607, 2023). "Darier’s disease develops due to a mutation in the gene encoding the intracellular calcium pump (ATP2A2) and is inherited in an autosomal dominant fashion." (PMID 38203406, 2023). "Darier disease is an uncommon autosomal dominant inherited disease, caused by a mutation in the ATP2A2 gene." (PMID 35853773, 2022). "Both the patient and his mother had Darier's disease, genetic screening revealed that the patient carried a heterozygous frameshift mutation in ATP2A2 gene, which was inherited from his mother." (PMID 35966859, 2022).
Darier disease (continued). "Haploinsufficient mutations of the ATP2A2 cause a rare autosomal dominant form of skin disorder, Darier disease." (PMID 34659328, 2021). "In fact, a mutation in the ATP2A2 gene, encoding sarco/endoplasmic reticulum calcium ATPase protein (SERCA2), causes Darier’s disease." (PMID 34830686, 2021). "A report of a family of Darier’s disease with mood disorders drew attention when the causative gene was identified as ATP2A2 (or SERCA2), which encodes a Ca2+ pump on the endoplasmic reticulum (ER) membrane and is important for intracellular Ca2+ signaling." (PMID 34104969, 2021). "Darier's disease (DD) is a rare, autosomal dominant genodermatosis that occurs due to mutations in the ATP2A2 gene on chromosome 12q23-24 that codes for sarco/endoplasmic reticulum calcium ATPase (SERCA), causing desmosomal breakdown and acantholysis." (PMID 32550053, 2020). "Darier disease (DD) is a hereditary skin disease caused by mutations in the ATP2A2 gene encoding the sarcoendoplasmic-reticulum ATPase 2 (SERCA2) calcium pump, which causes calcium dyshomeostasis and ER stress." (PMID 32042314, 2020). "As Darier disease in humans is caused by haploinsufficiency of ATP2A2, our genetic findings are in agreement with the clinical and histopathological data and support the diagnosis of canine Darier disease." (PMID 32354065, 2020). "Darier disease (DD) is a hereditary skin condition caused by mutations in the ATP2A2 gene encoding the sarco-endoplasmic reticulum ATPase 2 (SERCA2) calcium pump, which causes calcium dyshomeostasis and ER stress." (PMID 32042314, 2020). "Darier disease (DD) is a hereditary skin disease caused by mutations in the ATP2A2 gene encoding the sarcoendoplasmic-reticulum Ca2+ ATPase isoform 2 (SERCA2), which causes calcium dyshomeostasis and ER stress." (PMID 32327688, 2020). "Darier disease affects up to 1 in 30 000 people and is caused by mutations in the ATP2A2 gene, which encodes to the sarco/endoplasmic reticulum calcium-ATPase isoform 2 that pumps calcium into the endoplasmic reticulum." (PMID 29028823, 2017). "Heterozygous mutations in Atp2a2 cause Darier’s disease and significantly increase the risk of many psychiatric disorders including mood disorders, depression, and schizophrenia." (PMID 28893375, 2017). "Null mutations in one copy of ATP2A2, the gene encoding sarco/endoplasmic reticulum Ca2+-ATPase isoform 2 (SERCA2), cause Darier disease in humans, a skin condition involving keratinocytes." (PMID 26064889, 2015). "Mutations in ATP2A2 are known to cause neuropsychiatric phenotypes (including epilepsy) in patients with Darier disease." (PMID 25550428, 2015). "Darier’s disease (DD) is caused by heterozygous variants in the ATP2A2 gene." (PMID 41300841, 2025). "Mutations in the ATP2A2 gene lead to the ‘classic’ form of Darier’s disease." (PMID 40225094, 2025). "Darier's disease (DD) is an autosomal dominant genetic disorder caused by mutations in ATP2A2." (PMID 40062416, 2025). "Darier's disease (DD), also known as keratosis follicularis, is a rare hereditary acantholytic dermatosis, inherited in an autosomal dominant pattern, caused by mutations in the ATP2A2 [ATPase, Ca(++) transporting, cardiac muscle, slow-twitch 2] gene, with high penetrance but variable expressivity." (PMID 39950126, 2025). "Type 1 segmental, which has been renamed “mosaic form of Darier disease,” is the more common phenotype that is caused by a mutation in 1 allele of the ATP2A2 gene during embryogenesis in an otherwise healthy embryo, leading to segmental mosaicism and unilateral skin findings." (PMID 38406622, 2024). "Darier disease (DD) is a rare severe acantholytic skin disease caused by mutations in the ATP2A2 gene that encodes for the sarco/endoplasmic reticulum calcium ATPase isoform 2 (SERCA2)." (PMID 39060641, 2024).